CTLA4 (cytotoxic T-lymphocyte associated protein 4)
Diseases named in the same sentence as CTLA4 in open-access papers (continued):
Sharing a sentence is not in itself a finding about the gene and the disease.
tumor (continued). "TIM-3 also provides a new surface marker able to describe activated tumor infiltrating Tregs, which have been found to co-express higher levels of PD-1, CTLA-4 and the glucocorticoid-induced tumour necrosis factor receptor-related protein." (PMID 28404974, 2017). "In another study, i.v. injection of a replicating AdV expressing an anti-murine CTLA-4 mAb delayed tumor growth in syngeneic mouse models, and led to complete regressions when combined with a virus encoding GM-CSF." (PMID 28592330, 2017). "Whereas CTLA-4 antibodies lower the threshold for T cell activation (also of low affine tumor specific naive T cells), antibodies targeting the PD-1/PD-L axis aim at regulating effector T cell activity." (PMID 28073373, 2017). "We demonstrate that pre-treatment with a MEK inhibitor enhances the efficacy of anti-CTLA-4 in a CT26 pre-clinical tumor model." (PMID 28807001, 2017). "IPI inhibits the CTLA-4/B7 interaction, thus promoting costimulation and proliferation of Teff cells as well as their infiltration into the tumor." (PMID 28446908, 2017). "When these tumors were treated with checkpoint inhibitors against PD-1 and CTLA-4, a period of tumor shrinkage followed by tumor growth was observed." (PMID 28498806, 2017). "Coadministration of A2A antagonist with anti-CTLA4 mAb marked inhibited tumor growth and enhanced antitumor immune responses in a mouse melanoma model." (PMID 29184552, 2017). "Anti-immune pathways like PD-L1 and CTLA4 are used by the tumor to overcome immune system and they serve as immunotherapy targets." (PMID 28038471, 2017). "Only the combination of anti-CTLA4 checkpoint inhibitor immunotherapy with 20 Gy focal irradiation to the tumor site (referred to as CT) produced a significant decrease in tumor areas as compared to no treatment (NT) (p < 0.05, repeated measures)." (PMID 27893434, 2017). "CTLA-4 expression clearly contributes to perpetuate tumor immune escape by continuously inhibiting effector functions of tumor-infiltrating lymphocytes." (PMID 29023417, 2017). "Further, mice that rejected MOC1 tumors following treatment with CTLA-4 mAb alone or in combination with gMDSC depletion resisted engraftment when challenged with MOC1 tumor cells." (PMID 28915554, 2017). "After anti-CTLA-4 treatment, evidence of an immune response targeting tumor neoepitopes provided a genetic basis for anti-immune checkpoint response." (PMID 28620382, 2017). "The inhibition of CTLA4 can re-activate the known-tumor activities of cytotoxic T cells, and augmenting the immune system with a CTLA4 inhibitor significantly enhanced the effect of imatinib treatment." (PMID 28947997, 2017). "Based on these plots, we delineated ten different phenotypic clusters of antigen-specific T cells that are composed of cells specific for either neoantigen derived from anti-CTLA-4 treated and isotype control treated tumour bearing subjects." (PMID 28916749, 2017). "CTLA-4 is induced on mouse IL-2-activated NK cells and is expressed on splenic Kit+ and tumor-infiltrating NK cells in tumor-bearing mice." (PMID 29023417, 2017). "Immune checkpoint therapy based on either anti-CTLA-4 or anti-PD-1/PD-L1 blocking antibodies inactivates the brakes on T cells, allowing broad activation of T cells, including tumor-specific T cells." (PMID 27714433, 2017). "Some studies point to the idea that the expression of inhibitory ligands, such as CTLA-4 or PD-L1, by the tumor represents an adaptive response to tumor-specific T cells in the microenvironment." (PMID 26934557, 2017). "The addition of anti-CTLA-4 to the anti-PD-1 blockade induced a significant inhibition of tumor growth compared to single-agent treatment, which was significantly improved by vorinostat addition." (PMID 29371976, 2017). "iTSCM cells lose PD-1 and CTLA-4 expression, and produce a large number of tumour-specific effector cells after restimulation." (PMID 28530241, 2017).
tumor (continued). "These agents have shown the capability of inducing durable tumor regression with less grade 3 or 4 adverse events compared with CTLA-4 mAb and PD-1 mAb." (PMID 28299344, 2017). "In this study, animals bearing large CT26 tumours (>600 mm3) were treated with anti-PD-1 and anti-CTLA-4 antibodies, in combination with 5-AZA or entinostat." (PMID 28572863, 2017). "The use of monoclonal antibodies against the immune-checkpoints, such as CTLA-4 and PD-1, can decrease the tumor immunosuppression." (PMID 29213157, 2017). "CTLA-4 blockade using anti-CTLA4 monoclonal antibodies has become a promising therapeutic strategy for promoting anti-tumor immune response." (PMID 28428884, 2017). "In a mouse model, IDO expressed by the host immune cells has been shown to reduce the infiltration of tumor-reactive T cells in B16 tumors, inducing resistance to immunotherapy with mAbs targeting CTLA-4 and PD-1." (PMID 28404974, 2017). "The addition of gMDSC depletion to CTLA-4 blockade resulted in tumor rejection of all treated MOC1 tumor-bearing mice, resulting in significantly prolonged survival." (PMID 28915554, 2017). "Although current immunotherapies targeted at the immune checkpoints, PD-1 and CTLA-4, exhibit enormous potential to control cancer, there are still some tumor types and many patients that remain largely refractory to these therapies." (PMID 28545567, 2017). "Together, these events restored tumor sensitivity to treatment with antibodies against the checkpoint inhibitors PD‐1 and CTLA‐4." (PMID 27974353, 2017). "Strategies for next generation anti-CTLA-4 antibodies included non-fucosylated ipilimumab for enhanced activity via increased FcγR binding and a ProbodyTM version of anti-CTLA-4 for improved safety that localizes the drug activity to the tumor." (PMID 28716068, 2017). "The rationale is to release the brake imposed to bona fide tumor-reactive T cells by surface molecules like CTLA-4, whose induction is considered as a counter-regulatory mechanism required for self-limitation of any immune response." (PMID 27966460, 2017). "Except for poor T-lymphocytic response, the expression of CTLA4 by tumor cells also designated a poorer prognosis." (PMID 28038471, 2017). "The role of ICOS in anti-tumour tumour efficacy of CTLA-4 blockade was confirmed by mouse studies, where therapeutic efficacy of CTLA-4 blockade was severely compromised in ICOS-deficient mice." (PMID 28194010, 2017). "The MEK inhibitor trametinib was also found to synergise with adoptive T-cell transfer and anti-CTLA-4 therapies in mouse tumor models." (PMID 28807001, 2017). "Cytotoxic T lymphocyte-associated antigen 4 (CTLA-4), a potent immunoregulatory molecule, can down-regulate T-cell activation and inhibit anti-tumor immune response." (PMID 28099147, 2017). "The second group, focusing on tumor tissue-based markers such as expression profiles, genetic alterations, and tumor-infiltrating cells, was described in 52 studies for anti-CTLA-4 and 39 for anti-PD1." (PMID 29034210, 2017). "For example, in a subgroup of melanoma patients treated with ipilimumab, an anti-CTLA-4 monoclonal antibody, lesion enlargement preceded a decrease in tumor burden." (PMID 28915720, 2017). "In 1996, CTLA-4 inhibitors monoclonal antibody was firstly reported to lead to tumor regressions in murine model." (PMID 28536525, 2017). "Analysis of distant B16-F10 tumours from the animals treated with combination of NDV and anti-CTLA-4 therapy demonstrated tumour infiltration with various immune cell subtypes." (PMID 28194010, 2017). "This approach allows the activity of Ipilimumab to be targeted to T cells that strongly express CTLA-4 as a consequence of their specific stimulation in the presence of tumor cells." (PMID 27966460, 2017). "Treatment of MOC1 tumor-bearing mice with CTLA-4 mAb plus gMDSC depletion in the presence of cellular depleting mAbs revealed that tumor rejection is dependent upon CD8+ but not CD4+ or NK cells." (PMID 28915554, 2017).
tumor (continued). "Though Fc mediated ADCC or CDC activity was important for the depletion of CTLA-4 high Tregs, the blockade of CTLA-4/B7-1 (B7-2) to restore conventional T cell reactivity was also critical for its anti-tumor efficacy." (PMID 28978021, 2017). "In immunocompetent murine models, miR-138 treatment of GL261 gliomas reduced the expression of PD-1, CTLA-4, and FoxP3 in T cells, promoting tumor regression." (PMID 29299180, 2017). "These include cellular therapies (adoptive T-cell and dendritic cell therapy, cytokine-induced killer cells, tumor vaccines, and autologous tumor cell therapy) and checkpoint inhibitors (PD-1/L-1 and CTLA-4 inhibitors)." (PMID 28620466, 2017). "Although we found depletion of Tregs in our study, we cannot exclude an additional role for CTLA4 blockade on tumor-infiltrating T cells." (PMID 28646041, 2017). "We (M.M.G., J.P.W. and R.D.S.)have previously shown that besides CTLA-4 blocking, anti-PD-1 treatment rendered neoantigen-specific T cells capable of tumour rejection." (PMID 28916749, 2017). "These are reactivated after treatment with anti-PD-1 and/or anti-CTLA-4, and although they show some overlap, their transcriptional profiles are mostly treatment-specific, giving them the ability to mediate tumor rejection." (PMID 28361224, 2017). "Amongst the CD8 infiltrate, the frequency of PD-1, CTLA-4 and Tim-3 expressing cells was significantly elevated in tumour relative to the blood across the patient cohort." (PMID 28423034, 2017). "Several other components of the TME have also been associated with tumor growth and metastasis, such as VEGF, PD-1, and CTLA-4, and treatments targeting these TME factors are currently being explored in clinical trials." (PMID 28410227, 2017). "Here, the authors design a nanoparticle that simultaneously acts as a photothermal agent and an immune-adjuvant and demonstrate the anti-tumour efficacy in combination with anti-CTLA4 therapy in preclinical murine cancer models." (PMID 27767031, 2016). "A seminal preclinical study demonstrated that RT is synergistic with anti-CTLA antibody and induces systemic anti-tumor responses in a poorly immunogenic carcinoma refractory to anti-CTLA-4 monotherapy." (PMID 27660705, 2016). "In the tumor microenvironment, T cells with anti-tumor activity are functionally suppressed after receiving inhibitory signals through CTLA4 and PD1." (PMID 27551523, 2016). "This CTLA-4 aptamer-based targeting delivery of STAT-3 siRNA to T lymphocytes resulted in inhibition of tumor growth and of metastasis." (PMID 27413756, 2016). "In contrast, in tumor-bearing control mice and mice treated only with anti-CTLA-4 where tumor burden was high, ICOS expression was increased on both FoxP3+ Tregs and FoxP3− Teff cells." (PMID 26961085, 2016). "The highest level of CTLA-4 expression was found on tumor Tregs, which was similar to the OX40 expression pattern (both in percentage of positive cells and MFI)." (PMID 27195113, 2016). "Activation of naïve T cells (following specific antigen recognition) induces the expression of cytokines such as interferon-γ, which in turn induces CTLA-4 expression on surrounding immune and tumor cells." (PMID 27050369, 2016). "In contrast, in addition to a possible effect at the tumour site, CTLA-4 blockade is thought to enhance tumour-specific T cell responses." (PMID 27994647, 2016). "We demonstrate that pre-treatment with anti-CTLA4 antibodies provided optimal tumor control, while an alternate immunotherapy with anti-OX40, which targets recently-activated T cells, was optimal if delivered immediately following radiation therapy." (PMID 27281029, 2016). "The ability of ipilimumab-refractory disease to respond to pembrolizumab is probably a reflection of the different mechanisms by which anti-CTLA-4 and anti-PD-1 therapies stimulate an anti-tumor T-cell response." (PMID 26767073, 2016).
tumor (continued). "Cellular and murine models have been used to demonstrate that CTLA-4 blockade augments endogenous responses to several tumor types, leading to tumor cell death when utilized alone or in combination other therapeutic interventions." (PMID 27050369, 2016). "PD-1, as CTLA4, is expressed on T cells, but contrary to CTLA4, it is involved in the late phases of immune reactions and mostly within the tumor microenvironment." (PMID 28018902, 2016). "The potency of combined anti-CTLA-4 and anti-PD-1 is likely due to the effect of the antibodies on different cell populations within the tumor." (PMID 27610613, 2016). "CTLA4 aptamer-STAT3 siRNA inhibits tumor-associated Tregs and reduces tumor burden in multiple mouse tumor models." (PMID 27456457, 2016). "More interestingly, anti-PD-L1, albeit ineffective in combination with IL-15SA/IL-15RαSu-Fc in this tumor model, appeared to further improve survival when administered in conjunction with both IL-15SA/IL-15RαSu-Fc and anti-CTLA-4." (PMID 26910920, 2016). "Preclinical models support use of hypofractionated RT in daily doses of 6 to 8 Gy given 5 or 3 times, over a single high dose treatment of 20 Gy, in order to maximize likelihood of generating an effective anti-tumor immune response with anti-CTLA-4." (PMID 27660705, 2016). "Cytokine analysis at the MC38 tumor site revealed that IFN-γ was secreted at higher levels after CTLA-4 or PD-1 treatment compared to isotype control mAb, and IFN-γ secretion was further enhanced when the mAbs were combined." (PMID 27610613, 2016). "Antibody therapies blocking PD-1, PD-L1 and CTLA-4 function enhance anti-tumour immunity, leading to durable clinical responses for a subset of patients with melanoma, lung cancer and other tumour types." (PMID 26918344, 2016). "There is also evidence that the combination of both CTLA-4 antibodies and PD-1 antibodies results in better tumor outcomes than either antibody type alone." (PMID 27186886, 2016). "In the lymphatic tissues, anti-CTLA-4 antibody induces non-tumor-specific immune activation that is largely de novo induction of new responses." (PMID 27234522, 2016). "PD-1/CTLA-4 blockade markedly increases EBV-specific T cell responses, and is associated with enhanced tumor infiltration by CD4+ and CD8+ T cells." (PMID 27186886, 2016). "An increasingly recognized mechanism by which virally infected cells, as well as tumor cells, can overwhelm the T cell response is to induce T cell “exhaustion” by expressing ligands for the inhibitory T cell receptors, CTLA-4 and PD-1." (PMID 27186886, 2016). "NPC patients with high tumor CTLA-4 expression had a poorer prognosis than those with low expression." (PMID 26918337, 2016). "This is the basis for immune checkpoint blockade where antibodies such as ipilimumab (α-CTLA-4), pembrolizumab (α-PD-1) and nivolumab (α-PD-1) interfere with the engagement of the inhibitory ligand with the receptor to maximize anti-tumor immunity." (PMID 27066484, 2016). "Half the tumor-bearing mice that received anti-CTLA4 following radiation cleared the tumor with median survivals of 92 days for day 15 administration (p = 0.002 vs radiation alone) versus 53 days for day 19 administration (p = 0.07 vs radiation alone)." (PMID 27281029, 2016). "In other words, blocking the immunosuppressive effect of CTLA-4 can stimulate the proliferation of immune cells, which can induce or enhance anti-tumor immune response." (PMID 27783810, 2016). "Next we confirmed the role of CD4+ and CD8+ T cells in anti-PD-1 and anti-CTLA-4 treatment of MC38 tumor-bearing mice." (PMID 27610613, 2016). "The low tumor CTLA-4 expression group had more early stage (stage I–II) patients than the CTLA-4 high expression group (18.3% vs. 10.2%, p = 0.047)." (PMID 26918337, 2016).
tumor (continued). "In murine glioma models, combining radiation concurrently with anti-PD-1 and anti-CTLA-4 or 4-1BB (a costimulatory molecule) agonist yielded improved survival and increased tumor-infiltrating leukocyte (TIL) population, compared with either modality alone." (PMID 27774435, 2016). "The expression of inhibitory checkpoint receptors PD-1, Lag3, CTLA-4 increases in tumour infiltrating T lymphocytes, contributing to the dampening of the immune response." (PMID 27083002, 2016). "A Cox regression analysis confirmed the prognostic value of the tumor CTLA-4 expression in NPC patients, especially for the D-FFS of NPC patients." (PMID 26918337, 2016). "In order to find promising targets in diverse cancer types, we examined how tumor-infiltrating immune cells correlate with inhibitory molecules, including the receptors CTLA4, PD-1, LAG3, and TIM3, and the ligands PD-L1/2, B7-H3/4." (PMID 27549193, 2016). "Antibody blockade of CTLA-4 and PD-1 has resulted in dramatic reductions in tumor burden in many human subjects." (PMID 27610613, 2016). "After injection of the tumor-bearing mouse model with DNA vaccine, the plasmid carrying the fusion gene of CTLA4 and PSCA showed stronger inhibition of tumor growth than the plasmid expressing PSCA alone." (PMID 27783810, 2016). "Independently from the prognostic significance of PD-L1 expression, PD-L1/PD-1 receptor B7/CTLA-4 interactions are important immune escape mechanisms, allowing tumor progression." (PMID 27447625, 2016). "It is particularly encouraging that in mouse models, systemic Gem/Nab chemotherapy plus immunotherapy was able to initiate sufficient anti-tumor immune responses for tumor control with anti-CTLA4 plus anti-PD1 therapy." (PMID 27532020, 2016). "CTLA4 blockade would probably reduce the threshold of T-cell activation, perhaps favoring the priming of tumor-reactive T cells." (PMID 27783034, 2016). "The expression profiles of the inducible T cell co-stimulatory (ICOS) molecule were of particular interest because this T cell activation marker is known to increase on CD4+ T cells within the tumor and periphery following anti-CTLA-4 treatment." (PMID 26961085, 2016). "This tumor model is resistant to many immunotherapies such as anti-PD-L1 or anti-CTLA-4 when administered as a single agent." (PMID 28123897, 2016). "Our case is the first report of FDG-avid diffuse lymphadenopathy occurring with combined CTLA-4 and PD-1 blockade, with correlative pathology confirming benign lymphadenopathy and regression of cutaneous metastases." (PMID 27660712, 2016). "Cox regression analysis confirmed the prognostic value of tumor CTLA-4 expression, particularly for D-FFS, in NPC patients (p = 0.044)." (PMID 26918337, 2016). "Ex vivo treatment of HNSCC tumor-infiltrating lymphocytes with the anti-CTLA-4 mAb ipilimumab depleted Tregs and restored NK cell-mediated ADCC." (PMID 31093342, 2016). "An increase in CTLA-4-expressing lymphocytes was observed in some dogs in the other tumor group and was related to metastasis status in that group." (PMID 26901565, 2016). "Several preclinical tumour models are showing that CTLA-4 blockade in combination with DC vaccination primes immune response and potentiates a specific antitumour response." (PMID 27212807, 2016). "In contrast to the central immune inhibitory effects of CTLA-4, inhibition through PD-1 predominantly occurs at the periphery, with tumor cells up-regulating PD-L1 in response to local immune signals such as interferon-γ." (PMID 27959922, 2016). "Immune checkpoint blockade inhibits interaction of tumor cells with CTLA-4 or PD1; thus, blocking inactivation of T-cells." (PMID 29034103, 2016). "The combination of NDV with CTLA-4 blockade potentiated the systemic anti-tumour immune response, resulting in improved long-term survival of most co-treated animals." (PMID 26751469, 2016).